TOP2A (DNA topoisomerase II alpha)
Diseases named in the same sentence as TOP2A in open-access papers (continued):
Sharing a sentence is not in itself a finding about the gene and the disease.
liposarcoma (10 papers, 2012 to 2025). A usually painless malignant tumor that arises from adipose tissue. "miRs that inhibit DNA topoisomerase 2A (Top2A), such as miR-143, are implicated in drug resistance in dedifferentiated liposarcoma." (PMID 28978183, 2017). "In the present study we evaluated the expression of E-cadherin, beta-catenin and TOP2α proteins in a series of 71 liposarcoma cases and investigated potential associations of these molecules with clinical outcome." (PMID 22300273, 2012). "We consider that faint nuclear TOP2α expression in our series associates well to the limited activity of anthracyclins in liposarcomas and also the relatively favourable prognosis of this sarcoma subtype which still remains dismal." (PMID 22300273, 2012). "We evaluated the expression of E-cadherin, beta-catenin and TOP2α in a cohort of 71 liposarcoma cases and investigated for possible associations with pathological characteristics and clinical outcome." (PMID 22300273, 2012). "Restored miR-143 decreased the expression of Top2A, inhibited proliferation and induced apoptosis in dedifferentiated liposarcoma cells." (PMID 28978183, 2017). "Moreover, in liposarcoma, TOP2A was overexpressed, and knockdown of TOP2A reduced proliferation and invasion." (PMID 32368301, 2020). "In dedifferentiated liposarcoma, reduced expression of miR-143 increased nuclear expression of Top2A and cell proliferation, and this led to the dedifferentiated liposarcoma cells acquiring resistance to Top2A-targeted drugs." (PMID 28978183, 2017). "Considering the known tumour-promoting roles of TOP2A, PRC1, and PLK1, inhibiting these proteins by miR-143, therefore, helps inhibit liposarcoma progression." (PMID 39736850, 2025). "MiR-143 inhibits proliferation, induces apoptosis and cytokinesis of dedifferentiated liposarcoma cells by lowering BCL2, TOP2A, PRC1 and PLK1 expression." (PMID 28036291, 2017). "These genes include ZIC1, TOP2A, and AURKA, which have high expression levels across the liposarcoma spectrum." (PMID 25238053, 2014). "Functional assay revealed that miR-143 could repress the expressions of topoisomerase 2-alpha (TOP2A), protein regulator of cytokinesis 1 (PRC1), and polo-like kinase 1 (PLK1) to inhibit liposarcoma cell growth and trigger apoptosis." (PMID 39736850, 2025).
melanoma (10 papers, 2013 to 2025). A malignant, usually aggressive tumor composed of atypical, neoplastic melanocytes. "These genes included SKP2, TOP2A, SOX4, MAP2 and CTLA4, all of which have been associated with patient outcome in melanoma." (PMID 29193607, 2018). "High expression of metastasis-associated CD271-responsive genes NEK2, RAD51AP1, TOP2A and NGF in drug-resistant MeWo cells and their drug-dependent regulation, may have consequences for the priming of melanoma cells for metastasis." (PMID 28112719, 2017). "The study have suggested that TOP2A may play a crucial role in the development of melanoma." (PMID 38382096, 2024). "Further, we identified 110 CD271-responsive genes predominantly expressed in melanoma metastases, among them were NEK2, TOP2A and RAD51AP1 as potential drivers of melanoma metastasis." (PMID 28112719, 2017). "In addition, we identified Mesenchyme (COL1A1+), Endothelium (SOX18+, KDR+), proliferating cells (TOP2A+, MKI67+), and some off‐target cells; Glial (MSX1+, SOX2+), Melanoma (PMEL+, PLP1+), and Neuron (DLL3, HES6)." (PMID 35322595, 2022).
metastatic tumors (10 papers, 2014 to 2025). "TOP2A was associated with a decreased time to metastatic disease (HR 4.13; p = 0.044), decreased DSS (HR 3.51; p = 0.014), and decreased OS (HR 2.65; p = 0.012)." (PMID 36464833, 2023). "Given frequent TOP1 expression in metastatic tumors and association with TOP2A expression, use of a TOP1 inhibitor in combination with a TOP2A inhibitor may be considered for recurrent and metastatic medulloblastomas." (PMID 29869738, 2018). "In the Fred Hutchinson Cancer Research Center dataset, docetaxel-exposed tissues and metastatic tumors had higher TOP2A expression." (PMID 34782700, 2021). "TOP1 was found to be enriched in metastatic tumors (90%; 9/10) relative to posterior fossa cases (50%; 10/20) (p = 0.0485, Fisher exact test), and there was a positive correlation between TOP2A and TOP1 expression (p = 0.0472)." (PMID 29869738, 2018). "Top2a (Top2a) mRNA expression from our normalized RNA-seq counts was increased in metastatic tumors." (PMID 25605014, 2015). "We identify Top2a as a significantly up-regulated transcript in metastatic tumors from a transplantable PCa mouse model of spontaneous metastasis." (PMID 25605014, 2015). "Differential gene expression analysis revealed a significant increase of topoisomerase IIα, Top2a (Top2a) in metastatic tumors." (PMID 25605014, 2015). "Our RNA-seq data highlighted increased expression Topoisomerase IIα (Top2a) in murine metastatic tumors, which was validated in a human PCa dataset." (PMID 25605014, 2015). "Additionally, the differential expression levels of TOP2A were observed between various tumors and metastatic tumors compared with their matched normal tissues." (PMID 37980167, 2023). "To conclude, TOP2A is a potential prognostic marker as it is frequently elevated in PPGL displaying subsequent metastatic disease, and future studies in larger cohorts are warranted to determine if a TOP2A index as assessed by immunohistochemistry could be a marker of poor outcome." (PMID 36656469, 2023). "Of note, Topoisomerase type II alpha (TOP2A) was found over-expressed in the metastatic cases and could therefore in theory constitute a possible prognostic marker to identify patients with a potentially metastatic tumor." (PMID 36656469, 2023). "PPGL cases with metastatic disease (or exhibiting local recurrence) displayed a significantly higher expression of TOP2A mRNA as compared to non-disseminated PPGL (p = 0.008)." (PMID 36656469, 2023). "Tumor necrosis with fascin expression or the TOP2A ratio was not assessed, nor were the changes between initial CNB and post-neoadjuvant or metastatic disease." (PMID 40243780, 2025). "The aim of this study was to investigate whether TOP2A could be used as a marker of poor clinical outcome in PPGL and distinguish metastatic tumors from non-metastatic ones." (PMID 36656469, 2023).
osteosarcoma (10 papers, 2012 to 2025). A usually aggressive malignant bone-forming mesenchymal neoplasm, predominantly affecting adolescents and young adults. "We then performed a survival curve analysis to determine whether TOP2A or CDK1 levels were associated with osteosarcoma patients’ prognoses in the Therapeutically Applicable Research to Generate Effective Treatments dataset." (PMID 34156352, 2021). "More interestingly, the multiomic analysis pointed out the pivotal role of HDAC1 and TOP2A in osteosarcoma." (PMID 37457661, 2023). "Osteosarcoma patients with lower TOP2A levels exhibited significantly longer overall survival (OS) and progression-free survival (PFS) than those with higher TOP2A levels (P < 0.01)." (PMID 34156352, 2021). "We identified candidate drugs (CP724714, MP470, TGX221, and XMD8-85) for TOP2A in molecular subtypes of sarcoma (osteosarcoma and soft tissue)." (PMID 32784588, 2020). "Compared to adult cancers, the 17q21 amplicon, including TOP2A and ERBB2 genes, seems to be differentially implicated in the osteosarcoma chemoresponsiveness." (PMID 24216996, 2013). "The significant correlation between TOP1 and TOP2A gene copy variations reinforced the molecular basis of TOP1 and TOP2A linked expression in malignant osteoblasts and, consequently, in pediatric osteosarcomas." (PMID 24216996, 2013). "First, to understand the role of TOP2A in the osteosarcoma chemoresponsiveness, TOP2A amplicon containing also HER2/ERBB2 gene was studied in a homogeneously treated pediatric osteosarcoma tumor collection." (PMID 24216996, 2013). "We found that, compared to adjacentnormal tissues, osteosarcoma tumor tissues exhibited an overall highexpression of DNA metabolism-related genes, such as TOP2A, RRM2, andCLSPN, in most samples, indicating active DNA replication, repair,and other metabolic processes in osteosarcoma." (PMID 40834268, 2025). "TOP2A is a well‐studied and widely used gene target for osteosarcoma treatment." (PMID 37457661, 2023). "Surprisingly, there is no ERBB2 gene co-amplification and the patients harboring TOP2A amplification tend to show a worse survival, so TOP2A analyses remain a preliminary, but a good molecular approach for the evaluation at diagnosis of pediatric osteosarcoma chemoresponsiveness." (PMID 24216996, 2013). "Although TOP2A and TOP3A are different types of isomerases, one may speculate that amplification and overexpression of TOP3A has an oncogenic effect similar to that of TOP2A on the development of osteosarcoma and other cancers." (PMID 22292074, 2012). "Our multiomic data further indicated that TOP2A and HDAC1 played critical roles in osteosarcoma through different analysis." (PMID 37457661, 2023). "Our result suggested the biological and therapeutic significance of TOP2A and HDAC1 in osteosarcoma." (PMID 37457661, 2023). "Thus, CDK1 and TOP2A expression could be used to predict the prognosis of osteosarcoma patients." (PMID 34156352, 2021). "We then performed qRT-PCR to assess the expression of five hub genes (TOP2A, CDK1, MAD2L1, AURKA and RRM2) in human normal osteoblast cells and osteosarcoma cells." (PMID 34156352, 2021). "Subsequently, we performed qRT-PCR to measure TOP2A, CDK1, MAD2L1, AURKA and RRM2 expression in human normal osteoblast cells (hFOB 1.19) and osteosarcoma cells (MG63, U208 and 143B)." (PMID 34156352, 2021). "Although we showed an HDAC–SP1–TOP2A regulation axis in osteosarcoma, other HDAC and/or SP1 downstream pathways/targets beyond TOP2A may also contribute to the supra‐additive effect of HDAC inhibitors and DOX in osteosarcoma." (PMID 37457661, 2023). "Eight out of the 54 hub‐genes (ASPM, CENPF, KIF14, KIF20A, RCC1, SMC2, SRC, and TOP2A) were significantly decreased after NACT (criteria: |fold change| ≥ 2 and adjusted p value < 0.05), consistent with the central role of these hub genes in osteosarcoma." (PMID 37457661, 2023).
osteosarcoma (continued). "TOP2A and ECT2 were found up-regulated in osteosarcomas associated with lung metastases as compared with non-metastatic bone tumors." (PMID 36153320, 2022). "Interestingly, only TOP2A and HDAC1 were in the shared gene list of the previously identified 139 TSGs by transcriptomic and proteomic analysis, the 54 hub‐genes and the 282 target genes of effective drugs in osteosarcoma." (PMID 37457661, 2023). "As in other cancers, TOP2A gene status could be easily evaluated at a DNA level, where the quality controls and the independent reproducibility can be assessed, so a rapid and routinely done technique like FISH and/or QPCR could be performed for pediatric osteosarcomas." (PMID 24216996, 2013). "The combination of TOP2A and HDAC inhibitors has been assessed in clinical trials for soft‐tissue sarcoma and T‐cell lymphoma, but not in osteosarcoma (NCT00878800, NCT01902225), and showed good efficacy and tolerance." (PMID 37457661, 2023).
sarcoma (10 papers, 2012 to 2024). A usually aggressive malignant neoplasm of the soft tissue or bone. "This example demonstrates the fragility of regulatory mechanisms in sarcomas, as the over- and underexpression of other molecules can also affect downstream TOP2A activity and result in chemoresistance and poor prognosis." (PMID 34638362, 2021). "Sarcoma patients with elevated ALT had unfavorable risks (p < 0.038) coupled with a high expression of TOP2A, suggesting this as a potential drug target." (PMID 32784588, 2020). "The investigation of TOP2α in sarcomas has already drawn the attention of several investigators and our group." (PMID 22300273, 2012). "Our results show sarcoma subtype-specific patterns of TOP2A and SIRT1 expression." (PMID 34638362, 2021). "In sarcoma, TOP2A and ERK5 were inferred as potential targets." (PMID 32784588, 2020). "When the expression profile of TOP2A mRNA in human tumour or normal tissues was analysed using the GEPIA Platform, various tumour tissues, including sarcoma, showed higher levels of TOP2A expression than normal tissues." (PMID 38448751, 2024). "TOP2A (DNA topoisomerase II alpha) and FGFR1 (fibroblast growth factor receptor 1) were the most frequently upregulated targets across all analyzed sarcoma samples (n=14/20 and n=9/20 biopsies, respectively)." (PMID 29755686, 2018).
Sepsis (10 papers, 2016 to 2025). Sepsis is defined as life-threatening organ dysfunction caused by a dysregulated host response to infection. "TOP2A, topoisomerase II α, was found to be closely associated with sepsis-induced acute lung injury, which involves a variety of responses, including inflammatory responses and apoptosis." (PMID 39003404, 2024). "In sepsis‐induced acute lung injury, overexpression of miR‐125b‐5p inhibits TOP2A to alleviate the disease." (PMID 38661103, 2024). "Protein–protein interaction (PPI) network analysis highlighted TOP2A gene as the key regulator in the dysregulated gene network of sepsis-induced ARDS." (PMID 33904373, 2021). "Our PPI network analysis identified TOP2A as a key regulator in gene network of sepsis-induced ARDS." (PMID 33904373, 2021). "Through protein-protein-interaction (PPI) analysis of the dysregulated genes, we found that TOP2A gene is located at the central hub of the dysregulated gene network, indicating a key regulatory role in sepsis-induced ARDS." (PMID 33904373, 2021). "Collectively, our data unveil the potential of doxorubicin as a candidate treatment for sepsis-induced ARDS by targeting TOP2A." (PMID 33904373, 2021). "Among them TOP2A showed the highest degree of interactions, suggesting that TOP2A gene could be a key regulator in the DEGs network of sepsis-induced ARDS samples." (PMID 33904373, 2021). "Since Type II DNA topoisomerase can induce spontaneous double-strand break in genome, our data suggest that TOP2A mediated DNA damage response may be involved in the development of sepsis-induced ARDS, which required further experimental validation." (PMID 33904373, 2021). "Overall, our findings suggest that doxorubicin could be a potential therapeutic for sepsis-induced ARDS by targeting TOP2A, which requires further investigation and validation." (PMID 33904373, 2021). "We were also able to predict several therapeutic drug candidates for sepsis-induced ARDS using Connectivity Map (Cmap) database, among which doxorubicin was identified to interact with TOP2A with a high affinity similar to its endogenous ligand." (PMID 33904373, 2021). "Our PPI network analysis further unveils several key regulators like TOP2A, PAICS, HSPE1, HSP90AA1 and ACACA in the central hubs of dysregulated gene network in sepsis-induced ARDS." (PMID 33904373, 2021). "A study on transcriptome analysis predicts drug candidates for sepsis-induced ARDS; doxorubicin could be a potential therapeutic for sepsis-induced ARDS by targeting TOP2A." (PMID 34519633, 2021). "Genes including CCNB1, CCNB2 and TOP2A, as well as transcription factors like FOXM1 might be used as the novel gene therapy targets for sepsis related ARDS." (PMID 27090785, 2016). "Importantly, we further predicted multiple candidate drugs with the potential to reverse the signature of gene expression changes in sepsis-induced ARDS, among which doxorubicin may contribute to reverse the expression mode in ARDS by targeting TOP2A." (PMID 33904373, 2021).
adrenocortical carcinoma (9 papers, 2019 to 2023). "Furthermore, in TOP2A, the highest alteration frequency of “amplification” appeared in esophageal adenocarcinoma (>9%); of “mutation” appeared in skin cutaneous melanoma patients (>8%); and of “deep deletion” appeared in adrenocortical carcinoma (>3%)." (PMID 35873470, 2022). "Previous studies demonstrated that TOP2A was overexpressed in adrenocortical carcinoma and influenced tumor progression, because knockdown of TOP2A in adrenocortical carcinoma cells decreased cell proliferation and invasion." (PMID 32368301, 2020).
esophageal cancer (9 papers, 2014 to 2025). A primary or metastatic malignant neoplasm involving the esophagus. "A large-scale retrospective study has demonstrated that TOP2A high expression is associated with poor differentiation and neural invasion of esophageal cancer and is also an independent risk factor affecting the prognosis of esophageal cancer." (PMID 39234567, 2024). "Research has shown that reducing the levels of the long noncoding RNA DDX11-AS1 in esophageal cancer cells can lessen their resistance to paclitaxel by inhibiting TAF1/TOP2A." (PMID 39183398, 2024). "A recent study found that resistance of esophageal cancer cells to paclitaxel can be reduced by the knockdown of the long non-coding RNA DDX11-AS1 through TAF1/TOP2A inhibition." (PMID 35444699, 2022). "This also accords with our earlier observations, which shows that knocking down DDX11-AS1 decreases TOP2A expression and represses tumor growth of esophageal cancer." (PMID 33752668, 2021). "Silencing of lncRNA DDX11-AS1 could potentiate the inhibitory effects of paclitaxel on esophageal cancer xenografts in nude mice and suppress TOP2A expression, suggesting that lncRNA DDX11-AS1 may be a promising potential target for overcoming paclitaxel resistance of esophageal cancer." (PMID 34881242, 2021). "The expression levels of ERCC1, TYMS, TUBB3, RRM1 and TOP2A were determined using a microarray technique, while Spearman’s rank correlation analysis was used to determine the strength of the correlations between the expression levels of the biomarkers and the pathogenesis of esophageal cancer." (PMID 24926347, 2014). "ECA109 esophageal cancer cells were used to assess the impact of NEIL3 overexpression and TOP2A knockdown on proliferation, colony formation, migration, invasion, and apoptosis." (PMID 39910812, 2025).
invasive breast carcinoma (9 papers, 2008 to 2025). A carcinoma that infiltrates the breast parenchyma. "Co-amplification of HER2 and TOP2A serves as a sensitive indicator for selecting anthracycline-based chemotherapy for invasive breast cancer patients, who can benefit significantly from these treatments." (PMID 40777026, 2025). "The analysis of the expression of RRM2, CDC6, and TOP2A in normal and tumour breast invasive carcinoma using GEPIA showed significant increased expression of RRM2, CDC6 and TOP2A in tumour samples as compared to normal tissue." (PMID 36997866, 2023). "The observed significant prognostic value of both TOP2A and IGF2 in our sample supports the reliability of the performed analyses and urges further evaluation of the prognostic value of securin in invasive breast cancer." (PMID 18594525, 2008). "Between May 2005 and April 2015, a total of 643 consecutive non-metastatic invasive breast cancers were evaluated for TOP2A amplified using fluorescence in situ hybridization analysis (FISH) and for TOP2A overexpression using the immunohistochemistry assay." (PMID 29928479, 2018). "We found a striking trend toward increasing expression of TOP2A protein in this independent test set of histologically normal and benign breast tissues, ADH with or without synchronous invasive breast carcinoma, DCIS and invasive ductal breast carcinoma tissues, represented on the breast TMA." (PMID 21785684, 2011).